MEPCE (methylphosphate capping enzyme)
Description:
S-adenosyl-L-methionine-dependent methyltransferase that adds a methylphosphate cap at the 5'-end of 7SK snRNA (7SK RNA), leading to stabilize it. Also has a non-enzymatic function as part of the 7SK RNP complex: the 7SK RNP complex sequesters the positive transcription elongation factor b (P-TEFb) in a large inactive 7SK RNP complex preventing RNA polymerase II phosphorylation and subsequent transcriptional elongation. The 7SK RNP complex also promotes snRNA gene transcription by RNA polymerase II via interaction with the little elongation complex (LEC). In the 7SK RNP complex, MEPCE is required to stabilize 7SK RNA and facilitate the assembly of 7SK RNP complex. MEPCE has a non-enzymatic function in the 7SK RNP complex; interaction with LARP7 within the 7SK RNP complex occluding its catalytic center. Also required for stability of U6 snRNAs.
Synonyms: BCDIN3; FLJ20257
Tractability: Small molecule: a structure with a bound ligand is known. PROTAC: UniProt records ubiquitination sites on it; ubiquitination databases record sites on it; its protein half-life has been measured.
Gene: Protein-coding gene on chromosome 7 (100,428,322 to 100,434,126, forward strand). Ensembl gene ENSG00000146834.
Subcellular location: Nucleus
Subcellular location (Human Protein Atlas): Nucleoplasm; Cell Junctions
Gene Ontology:
Molecular function: 7SK snRNA binding; protein binding; RNA 5'-gamma-phosphate methyltransferase activity; RNA binding; RNA methyltransferase activity; S-adenosylmethionine-dependent methyltransferase activity; O-methyltransferase activity; snRNA binding; methyltransferase activity
Biological process: positive regulation of protein localization to Cajal body; positive regulation of snRNA transcription by RNA polymerase II; RNA methylation; snRNA metabolic process; snRNA modification
Cellular component: 7SK snRNP; nucleus; ribonucleoprotein complex
Genetic constraint (gnomAD): Loss-of-function variants: 9 observed, 47.2 expected, observed/expected ratio (o/e) 0.19, 90% interval 0.11 to 0.33. The synonymous counts are far from expectation, so gnomAD's model fits this gene poorly and the ratio says little. Missense variants: 826 observed, 875.83 expected, observed/expected ratio (o/e) 0.94, 90% interval 0.89 to 1. Synonymous variants: 477 observed, 381.44 expected, observed/expected ratio (o/e) 1.25, 90% interval 1.16 to 1.35.
Homologues: Orthologues: chimpanzee MEPCE (99% identical), macaque MEPCE (98% identical), dog MEPCE (92% identical), pig MEPCE (90% identical), guinea pig MEPCE (90% identical), mouse Mepce (87% identical), rabbit MEPCE (86% identical), rat Mepce (83% identical), tropical clawed frog mepce (50% identical), zebrafish mepcea (42% identical), zebrafish mepceb (39% identical), Drosophila melanogaster bin3 (30% identical), and 2 more. Paralogues in human: BCDIN3D (10% identical).
Diseases named in the same sentence as MEPCE in open-access papers:
MEPCE is named in the same sentence as 14 diseases in open-access papers, as found by Europe PMC text mining. Sharing a sentence is not in itself a finding about the gene and the disease. The quoted sentences say what the papers report.
breast carcinoma (2 papers, 2019 to 2024). "Both genes have not yet been associated with rare Mendelian disorders, however, MEPCE was found to be overexpressed in highly tumorigenic breast cancer stem cells and promotes cellular invasion." (PMID 31467394, 2019). "In the breast cancer cell line MDA-MB-231, the genes ID2 and ID3 have been demonstrated to be under the control of P-TEFb, and reduced P-TEFb recruitment/activity has been suggested to underlie downregulated expression of ID2 and ID3 upon MEPCE depletion." (PMID 31467394, 2019).
developmental delay (2 papers, 2019 to 2022). "We report a boy with global developmental delay and seizures carrying the de novo MEPCE nonsense variant c.1552 C > T/p.(Arg518*)." (PMID 31467394, 2019).
cancer (4 papers, 2021 to 2025). A tumor composed of atypical neoplastic, often pleomorphic cells that invade other tissues. "Emerging evidence suggests that some CDK9-related negative regulators (e.g., HEXIM 1/2, LARP7, and MePCE) are also involved in CDK9-related diseases, e.g., cancers." (PMID 35088192, 2023). "MEPCE is a methyltransferase that adds a monomethyl cap to small nuclear RNA, and CD70 is expressed readily on tumor cells and enhances cancer and regulatory T cell survival." (PMID 40078282, 2025). "Furthermore, NBDep identified two putative non-missense driver genes MEPCE and TMEM41A that were not previously known to be cancer driver genes." (PMID 38195844, 2024).
MEPCE also shares sentences with these, for which no sentence is quoted: neurodevelopmental disorder (2 papers); tumor (2); Alazami syndrome (1); COVID-19 (1); gastrointestinal disease (1); glioma (1); Intellectual disability (1); leukemia (1); lung carcinoma (1); Obesity (1); schizophrenia (1).